AFP (alpha fetoprotein)
Diseases named in the same sentence as AFP in open-access papers (continued):
Sharing a sentence is not in itself a finding about the gene and the disease.
tumor (continued). "Although HCC is diagnosed using blood tumor markers, alpha-fetoprotein (AFP), protein induced by vitamin K absence-II (PIVKA-II), and imaging tests such as ultrasonography and CT, current tests still fail to detect minute HCCs." (PMID 37910585, 2023). "Univariate and multivariate analyses demonstrated that tumor size (adjusted HR 2.13, P<0.001), AFP (adjusted HR 1.67, P<0.001), albumin (adjusted HR 1.67, P<0.05) and PS (adjusted HR 0.61, P<0.001) were predictors of OS." (PMID 37434986, 2023). "Testicular tumor markers, including serum beta–human chorionic gonadotropin (β‐hCG), alpha–fetoprotein (AFP), and lactate dehydrogenase (LDH) were all within normal limits." (PMID 37361656, 2023). "Patients treated with HAIC had significantly higher serum AFP levels and larger tumor sizes (p = 0.004 and p = 0.027, respectively) than those treated with AB." (PMID 37686509, 2023). "The combination of AFP, tumor location, and CT attenuation values of tumors at the portal venous phase showed excellent performance in differentiating GHA from GA." (PMID 37538113, 2023). "In univariate logistic regression analysis, it is shown that tumor size, AFP level, rim APHE, targetoid restriction on DWI, and number of tumors were correlated with recurrence in the training group." (PMID 36816925, 2023). "In the case of patient 23, PIVKA-II levels increased abruptly, even before the detection of tumour recurrence by imaging, while AFP levels remained within the reference range." (PMID 37024609, 2023). "Complete tumor necrosis was found in 26.1% (18 of 69) and 6.3% (2 of 32) of patients with an initial AFP level under and over 100 ng/mL, respectively (p = 0.020)." (PMID 37568778, 2023). "Results revealed elevated liver injury biomarkers ALT, AST, ALP, and tumor biomarkers AFP and GGT, and marked nodularity of livers of HCC-M." (PMID 37835585, 2023). "The increased level of RRM2 expression were positively correlated with a higher grade of T stage (P <0.05), Pathologic stage (P <0.05), tumor status (P <0.01), histologic grade (P <0.001), and AFP levels (P <0.001)." (PMID 37056349, 2023). "The untreated group also had higher serum AFP levels, higher tumor counts, larger tumors, and greater portal vein invasion at diagnosis (P < 0.001)." (PMID 37035191, 2023). "In this study, serum SP70 level, serum AFP level, tumor diameter and microvascular invasion (MVI) were independently correlated with RFS." (PMID 37091138, 2023). "Age, naïve or recurrence, sum of the size of the largest tumor nodule, the number of nodules, total bilirubin, albumin, AFP and DCP were selected as independent predictors of survival." (PMID 38007597, 2023). "Successful conversion surgery, sex, hapatic vein invasion, BCLC stage, baseline tumour size, AFP levels and maximum therapeutic response were independent prognostic factors for PFS." (PMID 37180098, 2023). "As European guidelines recommend, three biomarkers, β-human chorionic gonadotropin (β-hCG), lactate dehydrogenase (LDH), and AFP, should be measured on schedule according to treatment protocols and tumor stage." (PMID 37781207, 2023). "In clinical trials, cyclical administration in AFP (nAFP or rhAFP) and AFPR vaccines causes dysfunction of MDSCs, intensification of immune response, tumor destruction and prolongation of life." (PMID 36768863, 2023). "ATBF1, encoded by ZFHX3, negatively regulates AFP and MYB, positively regulates CDKN1A expression, and has been reported as a tumour suppressor gene in other types of cancer." (PMID 38104198, 2023). "In our study, we found that both the AFP value and total tumor size had an impact on the recurrence of HCC." (PMID 37909200, 2023). "Several studies have investigated the relevance of alpha-fetoprotein (AFP) tumour markers in managing these patients with a higher risk of recurrence in patients with high AFP levels." (PMID 37175054, 2023).
tumor (continued). "TARE-ineligible patients share similar features to TACE-refractory patients, such as high MoRAL scores or high AFP levels and large tumor sizes." (PMID 36925930, 2023). "We found improvements in the prediction efficiency of Milan criteria, MELD score, and AFP level when incorporating tumor micronecrosis." (PMID 36698095, 2023). "Histological examinations of the resected specimen from the both sites showed the same findings, as a high nucleus-to-cytoplasm ratio in the tumor cells, as well as immunohistochemically positive findings for chromogranin A, synaptophysin, and AFP." (PMID 37721573, 2023). "The results indicated that EST altered the levels of tumor markers (AFP, CEA, and anti-dsDNA) and liver biomarker function (ALT, AST, ALP, ALB, and T. protein)." (PMID 37048097, 2023). "It was found that high TF was closely connected to AFP (p = 0.033) and the tumor size (p = 0.034) and number (p = 0.020)." (PMID 36614249, 2023). "Patients with PVTT had increased tumor size (P = 0.000), higher Edmonson grade (P = 0.030), higher serum AFP levels (P = 0.004), and consequently higher BCLC stage (P = 0.000)." (PMID 37160624, 2023). "In Japan, three tumor markers (TMs), namely, alpha-fetoprotein (AFP), fucosylated AFP (AFP-L3), and des gamma-carboxy prothrombin (DCP), can be used not only for surveillance of HCC, but also for assessment of the malignant potential of HCC in Japan." (PMID 37686624, 2023). "In our study, the patient in Case 1 seemed sensitive to FOLFIRI combined with bevacizumab treatment, resulting in a substantial decrease in serum AFP and significant tumor shrinkage." (PMID 37950062, 2023). "Another study of patients who underwent transarterial chemoembolization for HCC (CP class A/B: 45.9%/54.1%) revealed GNRI <98, tumor number ≥ 2, tumor size ≥5 cm, TACE times <3, and alpha-fetoprotein ≥400 as independent risk factors for poor prognosis." (PMID 37799767, 2023). "Among these factors, treatment type, Child–Pugh class, pretreatment AFP level, and tumor size remained significant in the multivariable analysis." (PMID 37370774, 2023). "Secreted by ~70% of patients with HCC, AFP is a recognized tumor marker for HCC and an indicator for prognostic." (PMID 36562786, 2023). "In the remaining part of this section, we briefly outline the innovative therapeutic approaches utilizing the high expression of GPC3 and AFP to identify tumor cells." (PMID 38173713, 2023). "Both AAV8 viral vectors equally transduced hepatocytes at ~60% as shown by the reporter GFP expression including AFP+ tumor cells." (PMID 37156770, 2023). "Common Tumor markers for gastrointestinal and hepatic tumours, like Alpha-Fetoprotein (AFP), Carcinoembryonic Antigen (CEA), and CA19-9, are commonly negative." (PMID 37386646, 2023). "A large body of studies have demonstrated that elevated AFP levels in HCC patients were correlated with poor tumor differentiation, microvascular invasion, early recurrence, and poor prognosis." (PMID 36814805, 2023). "The survival calculator collects variables, such as age, sex, AFP level, tumor grade, tumor stage, tumor size, surgery, and chemotherapy." (PMID 38001570, 2023). "There are also reports of AFP‐producing tumours of germ cells (mainly the yolk sac, ovaries and testis), the urinary tract, the stomach, the bile duct and the pancreas in human (El‐Bahrawy, 2011)." (PMID 36495211, 2023). "Several tumor associated antigens (TAAs) expressed in liver tumor cells have been exploited for CAR-T cell therapy, including GPC-3, AFP, and CEA." (PMID 37665421, 2023). "Compared to Ufl1f/f mice, higher levels of the tumor marker alpha-fetoprotein (AFP) were also seen in Ufl1Δ/Δhep livers, as well as a ~ 30% increase in Ki67-positive cells, which is strongly indicative of rapid tumor growth." (PMID 37131258, 2023).
tumor (continued). "In multivariable analyses, the groups, according to LRT number, AFP response to LRT, and largest tumor size, independently predicted tumor recurrence; moreover, AFP response to LRT and AJCC T stage predicted overall survival." (PMID 36900345, 2023). "and study the relation between the genotypic frequencies for these gene and the biochemical measurements, hematological parameters and the tumor marker Alpha Feto Protein (AFP)." (PMID 37353775, 2023). "Patients were divided into two groups (high and low) according to the threshold of the median value of each tumor marker (AFP = 2 and HCG = 1)." (PMID 37848723, 2023). "Different diagnostic modalities were used such as ultrasonography of the whole abdomen, contrast-enhanced computed tomography abdomen pelvis and tumour markers of betahuman chorionic gonadotropin and alpha-fetoprotein." (PMID 37203966, 2023). "In TCGA cohort, CEP55 expression was correlated with age, serum AFP level, pathologic stage, histologic grade, and tumor recurrence (p < 0.05)." (PMID 37484531, 2023). "In patients with HCC, we developed and validated the FAIL-T score, which included routine imaging and laboratory parameters such as AST, ALT, AFP, tumor size, and tumor number." (PMID 37200967, 2023). "Our study retrospectively analyzed data and screened six risk factors, including AFP, LDH, aMAP score, diameter of main tumor, number of intrahepatic lesions, and treatment, that affect prognosis." (PMID 37283795, 2023). "Serum levels of several tumor markers were elevated; alpha-fetoprotein (AFP) (19.6 ng/ml, normal range < 10 ng/ml), carbohydrate antigen 19–9 (40 U/ml, normal range < 37 U/ml) and pro-gastrin-releasing peptide (103.6 pg/ml, normal range < 67 pg/ml)." (PMID 37027114, 2023). "The nomogram to predict RFS was built using five independent prognostic factors, namely, age, tumor number, postoperative AFP level, postoperative PIVKA-II level, and ECOG PS." (PMID 37689775, 2023). "Current treatment of paediatric HB is based on clinical risk stratification as, until recently, most tumours were diagnosed based on radiology and elevation of the tumour marker Alpha fetoprotein (AFP), with histology only being analysed following resection." (PMID 37958356, 2023). "They reported a concomitant increase in AFP levels with increased Hep3B tumor size, providing a minimally invasive method for monitoring tumor growth by measuring serum AFP levels." (PMID 37215109, 2023). "According to national guidelines, monthly clinical examinations with sonographic control and determination of the tumor markers AFP, HCG and CA 125 for six months after the operation was recommended." (PMID 36873804, 2023). "Ultrasound with an AFP serum assay is recommended for surveillance because a meta-analysis demonstrated that ultrasound alone had low sensitivity in detecting early-stage tumor in cirrhotic patients." (PMID 36831565, 2023). "Considering the predictive value of a single factor is limited, the predictive model combining the GLR and SII with tumor load and AFP level was established and demonstrated a good predictive value in both the development and validation cohorts." (PMID 37152021, 2023). "Alpha fetoprotein level, systemic inflammation response index, alanine aminotransferase, tumour diameter and portal vein tumour thrombus were also confirmed to be independent prognostic factors of HCC early recurrence in patients with MVI who underwent TACE." (PMID 37730533, 2023). "In the aspect of tumor markers, the median serum AFP level was 24.05 ng/mL (range: 2.3–57,125.2), and the median serum prothrombin induced by vitamin K absence-II level was 886.5 mAU/mL (range: 19–213,066)." (PMID 36765554, 2023). "In our study, tumor to liver SUV ratio (TLR) of the primary tumor was statistically significantly higher in Milan out tumors, “up-to-seven” out tumors, Grade 3 tumors, AFP level > 400 ng/ml and lesions of a diameter of 5 cm or more." (PMID 35451699, 2023).
tumor (continued). "The previously referenced study by deLemos indeed found that AFP levels were lower in ALD-HCC despite identical maximal tumor size." (PMID 36975484, 2023). "Multiple tumours, extrahepatic metastases, and AFP > 200 ng/ml were used for intrahepatic metastases." (PMID 36910605, 2023). "Laboratory tests and serum tumor markers were sent, and the AFP level incidentally returned unmeasurable (>200,000 ng/ml - reference range ≤ 8.0 ng/ml)." (PMID 40028484, 2023). "They found that only serum AFP elevation, age, and pathological tumor stage were predictive for overall survival (OS) (p < 0.0001)." (PMID 37781207, 2023). "AFP, size of maximum tumour diameter and the number of lesions within the liver were recorded at the time of the MDT discussion." (PMID 37989352, 2023). "The ORR was 60.9% and the risk of early ORR was independently predicted by AFP, portal vein tumor thrombus (PVTT), tumor number, and size in both the training (C-index = 0.853) and test (C-index = 0.800) cohorts." (PMID 36875116, 2023). "Due to the positive relationship between AFP levels and tumor burden, cut-off lowering can increase the sensitivity for early-stage detection." (PMID 37720239, 2023). "Including age, NEUT%, Cr, BMI, excision method, AFP, TBIL, PT, intraoperative blood loss, perioperative blood transfusion, tumor size, surgical mode, and bile leakage." (PMID 37046206, 2023). "We analyzed the correlation between MTMR2 expression levels and clinical parameters, including AFP level, tumor stage, Histologic grade, TMN stage, tumor status, gender, and age." (PMID 37907649, 2023). "As a marker of GCTs, the AFP is an important indicator for diagnosis, tumor burden assessment, and monitoring for recurrence during follow-up." (PMID 38001671, 2023). "For multiple tumors, when the diameter of the largest tumor was less than 7 cm and the serum AFP level was less than 400 ng/mL, the patient tended to be MVI negative (H)." (PMID 37118720, 2023). "Hanley-McNeil analysis showed that the scoring model was also significantly better than the GLR, SII, tumor number and AFP in the validation cohort (P=0.006, 0.023, <0.001, 0.044, respectively), with a sensitivity of 71.0% and specificity of 72.2%." (PMID 37152021, 2023). "For example, the sensitivity and specificity of various serum tumor markers, including alpha-fetoprotein (AFP) and carbohydrate antigen 19-9 (CA19-9), are unsatisfactory." (PMID 38001633, 2023). "These variables included age, gender, serum TB, albumin, AST, ALT, platelet counts, AFP level, tumor size, and BCLC stage." (PMID 38003232, 2023). "Tumor biomarkers, such as alpha-fetoprotein (AFP), carcinoembryonic antigen (CEA), carbohydrate antigen 19-9 (CA19-9), and carbohydrate antigen 125 (CA125), were all negative." (PMID 37492622, 2023). "The AFP, a vital tumor marker for HCC detection, has limited sensitivity in identifying early and small HCC." (PMID 37373013, 2023). "Initially, the patient was diagnosed with a germ cell tumor based on a high serum AFP level and imaging findings, and a CT-guided biopsy from the main tumor was performed for diagnosis confirmation." (PMID 37721573, 2023). "According to Cox proportional-hazard regression, univariate predictors of post-resection recurrence were AFP, number of tumor nodules, largest nodule size, vascular invasion, and capsular involvement." (PMID 37173900, 2023). "After performing a chi-square test analysis, we discovered a significant correlation between ORC6 expression and tumor histological grade, alpha-fetoprotein (AFP) content, and vascular invasion in LIHC." (PMID 37901236, 2023). "Clinical data from patients with HCC, such as tumor size, tumor number, tumor distribution, and preoperative AFP level, are sparse recorded in TCGA database." (PMID 36710413, 2023). "AFP decline demonstrated acceptable discrimination for predicting tumor recurrence, with an area under the ROC curve of 0.641 (p = 0.05)." (PMID 36900345, 2023).
tumor (continued). "The multivariate Cox regression analysis identified primary tumor in the mediastinum and AFP level ˃ 10,000 ng/mL as independent adverse prognostic factors (χ2 = 13.4262, p < 0.0.01; χ2 = 5.2766, p = 0.0216)." (PMID 38001671, 2023). "Presently, alpha-fetoprotein (AFP) is widely applied as a non-invasive monitoring biomarker of HCC tumor burden and aggressiveness." (PMID 38993841, 2023). "The expression of Asns has been observed to be elevated in HCC tumor tissues and closely correlates with serum α-fetoprotein (AFP) levels, tumor size, microscopic vascular invasion, as well as tumor encapsulation." (PMID 36980965, 2023). "This easy-to-use AFP ratio-based nomogram precisely predicted tumor recurrence in HCC patients after curative resection." (PMID 37124520, 2023). "Considering that AST, WBC, PLT, AFP and tumor size were significantly different between patients with PS0 and PS1 as well as that AFP, tumor size and albumin were predictors of OS, we included these variables in the PSM analysis." (PMID 37434986, 2023). "Some studies have reported a significant correlation between CD133 expression and the clinicopathological characteristics of HCC, including tumor grade, tumor stage, AFP serum level, malignant potential, a higher recurrence rate and a shorter overall survival." (PMID 36674932, 2023). "In the present nomogram, independent prognostic factors for tumor number, previous surgical resection, AFP level, PLT level, and ALP level were included." (PMID 37287040, 2023). "While AFP is elevated in less than half of patients with HCC, it is associated with tumor aggressiveness and worse prognosis." (PMID 38012205, 2023). "The characteristics of the tumor (multinodular disease and high AFP levels), possibly reflecting HCC malignancy and its ability to metastasize, seemed related to a worse prognosis." (PMID 36980538, 2023). "A recent study suggested that AFP levels should be evaluated differently based on the tumor diameter (cm) and number." (PMID 37909200, 2023). "Exosomes derived from alpha-fetoprotein (AFP)-expressing DCs activate specific CD8 antitumor immune responses in tumor tissues." (PMID 37183207, 2023). "The value of AFP decreased in 81.4% (92/113) of patients after surgery, but AFP increased again with tumor recurrence or metastasis." (PMID 37161409, 2023). "Other studies have reported that AFP, PIVKA-II, and CA19-9 levels, vascular invasion, tumor number, MVI, and age are closely associated with the risk of recurrence, and another study revealed an association between ECOG PS and poor RFS in patients with HCC." (PMID 37689775, 2023). "Our study also found that M-CTC positivity was associated with several features of HCC malignancy, including high AFP, larger and multiple tumors, poor tumor differentiation, incomplete tumor capsule, and the presence of MVI and PVTT." (PMID 36600214, 2023). "The AFP model is superior in predicting tumor recurrence in HCC patients with > 3 tumors prior to LT." (PMID 36967432, 2023). "In another study, phenylethanol glycosides from Cistanche have also been shown to reduce liver injury in H22 tumor-bearing mice and to improve immune function by reducing AFP levels, thereby adversely affecting tumor growth." (PMID 36814512, 2023). "Univariate and multivariate Cox regression analyses conducted to identify independent prognostic factors revealed nine such factors, including age, sex, tumor grade, surgery, chemotherapy, tumor size, and AFP level." (PMID 38001570, 2023). "Before and after neoadjuvant treatment, we routinely detected serum tumor markers, such as AFP, CEA, CA125, CA153 and CA199." (PMID 36793595, 2023). "Univariate analysis showed log10(tumor size), log10(AFP), log10(bilirubin), log10(ALT), log10(AST), 1/creatinine, vascular invasion (VI), and extrahepatic spread (EHS) were significantly correlated with OS." (PMID 36562786, 2023).